DNMT3A (DNA methyltransferase 3 alpha)
Diseases named in the same sentence as DNMT3A in open-access papers (continued):
Sharing a sentence is not in itself a finding about the gene and the disease.
lupus (5 papers, 2013 to 2023). "Reduced Dnmt1 and/or Dnmt3a/b expression has been correlated with the global DNA hypomethylation in the human lupus." (PMID 38153351, 2023). "Reduced expression/activity of DNMT1 and/or DNMT3a/3b has been identified in the PBMCs or CD4+ T cells of human patients with lupus, which contributed to the DNA hypomethylation in human lupus cells." (PMID 38153351, 2023). "It has been reported that DNMT1 and/or DNMT3a/3b expressions were significantly decreased in human lupus PBMCs and CD4+ T cells when compared to those of healthy controls, which correlated with the global DNA hypomethylation in the cells." (PMID 34062726, 2021). "Significant increase in DNMT3A (p < 0.001) was shown in lupus patients when compared to age-matched healthy controls." (PMID 23054340, 2013). "However, our study found that a subset of African American lupus patients receiving DHEA therapy showed decreases in DNMT3A expression." (PMID 23054340, 2013). "Nevertheless, other studies demonstrated unchanged DNMT1 and even increased DNMT3a/3b expression in human lupus PBMCs or CD4+ T cells, despite the consistency of DNA hypomethylation in these lupus cells." (PMID 34062726, 2021). "Real-time PCR analyses of DNMT1, DNMT3A and DNMT3B in peripheral blood mononuclear cells from a cohort of African American and European American lupus and non-lupus women were conducted." (PMID 23054340, 2013). "A subset of AA women on DHEA therapy showed a significant decrease (p < 0.05) in DNMT3A expression in comparison to lupus patients not on the therapy." (PMID 23054340, 2013). "Furthermore, examining those lupus patients on DHEA therapy, it was found that African American women had a significant decrease in expression of DNMT3A." (PMID 23054340, 2013). "However, unchanged Dnmt1 expression and even increased Dnmt3a/b gene expression have also been identified in human lupus PBMCs or CD4+ T cells in different studies, despite the consistency of DNA hypomethylation in these lupus cells." (PMID 38153351, 2023).
myelofibrosis (5 papers, 2012 to 2024). A partial or complete replacement of the bone marrow stroma by fibrous tissue. "Additionally, loss of Dnmt3a in hematopoietic stem/progenitor cells in conjunction with Jak2V617F mutation led to lethal myelofibrosis by promoting activated inflammatory signaling." (PMID 39330574, 2024). "Activated TNFα pathways were also confirmed by RNA-seq analysis in patients suffering from EZH2- or DNMT3A-deficient myelofibrosis compared to non-mutant controls." (PMID 32604862, 2020). "However, genomic studies of patients with myelofibrosis treated long-term with RUX as standard of care has not identified clear selection biases of preleukemic clones with DNMT3A mutations." (PMID 40552132, 2024).
Myocardial fibrosis (5 papers, 2023 to 2025). "Zhao discovered that low-intensity pulsed ultrasound treatment can reverse myocardial fibrosis caused by prolonged hypoxia via the TRAAK-mediated HIF-1α/DNMT3a signaling pathway." (PMID 39091919, 2024). "MiR3695p overexpression directly inhibits DNMT3A, induces aberrant DNA methylation of Patched1, and suppresses cardiac fibroblast proliferation and myocardial fibrosis levels." (PMID 37008904, 2023). "Another study showed that DNMT3A directly inhibits miR200b expression, which promotes cardiac autophagy and ultimately affects the development of myocardial fibrosis in a mouse model of aortic constriction." (PMID 37008904, 2023).
myocardial infarction (5 papers, 2019 to 2024). Gross necrosis of the myocardium, as a result of interruption of the blood supply to the area, as in coronary thrombosis. "8,9 Taken together, these findings suggest that CHIP, at least mediated by mutations in the most prevalent driver genes DNMT3A and TET2, may contribute to the development of CHF in patients after myocardial infarction." (PMID 30566180, 2019).
nasopharyngeal carcinoma (5 papers, 2013 to 2022). A carcinoma arising from the nasopharyngeal epithelium. "LMP1 up-regulates DNMT1, DNMT3A, and DNMT3B in EBV-associated nasopharyngeal carcinoma (latency II)." (PMID 32841292, 2020).
periodontitis (5 papers, 2020 to 2025). An acute or chronic inflammatory process that affects the tissues that surround and support the teeth. "For example, when adjusted for age and sex, the prevalence of stage IV periodontitis in carriers with DNMT3A mutations was (average marginal effect [AME]) 11 percentage points (95% confidence interval [CI] = 0.0–21.5) higher than in those without CHIP." (PMID 38838669, 2024). "CHIP due to DNMT3A mutations was significantly associated with a diagnosis of severe periodontitis (stage IV vs. stages I–III), as well as quantitative measures of “clinical attachment loss” and “gingival inflammation”." (PMID 38838669, 2024). "Compared to control samples, the methyltransferases DNMT1, DNMT2 and DNMT3B were significantly downregulated in periodontitis samples, while significantly higher DNMT3A expression was observed in periodontitis samples." (PMID 40267082, 2025). "DNMT3A-driven CHIP exacerbated periodontitis not only by enhancing inflammatory osteoclastogenesis but also by negatively impacting the host’s capacity to resolve the periodontal lesion." (PMID 38838669, 2024). "Our study has shown that DNMT3A-driven CHIP in mice causes naturally occurring periodontal inflammation and bone loss, as well as exacerbates experimentally induced periodontitis and arthritis." (PMID 38838669, 2024). "DNMT3A-driven clonal hematopoiesis and, subsequently, periodontitis were suppressed by rapamycin treatment." (PMID 38838669, 2024). "Similar transcript levels of DNMT1 and DNMT3a are expressed in gingival biopsies from periodontitis patients and healthy controls." (PMID 33256844, 2020). "The functional role of DNMT3A R878H in periodontitis was also confirmed using mice models." (PMID 39682303, 2024). "In conclusion, DNMT3A CHIP is associated with higher prevalence and severity of periodontitis." (PMID 38838669, 2024). "Our findings that DNMT3A-driven CHIP increases the severity of experimental periodontitis and arthritis and earlier mouse studies linking CHIP and cardiometabolic disorders suggest that CHIP may be a common mechanistic basis for inflammatory comorbidities in old age." (PMID 38838669, 2024). "Overall, expansion of Dnmt3a-CHIP clones and infiltration of peripheral tissues with mutant leukocytes aggravates experimentally induced periodontitis and arthritis." (PMID 38838669, 2024). "In gingival fibroblasts, DNMTs are also regulated by inflammatory mediators that play a central role in periodontitis pathogenesis: IL-1β upregulates DNMT1 and downregulates DNMT3a expression, whereas exposure to PGE2 leads to downregulation of both DNMT1 and DNMT3a." (PMID 33256844, 2020).
renal cell carcinoma (5 papers, 2017 to 2025). "Sohlh2 functions as a tumor suppressor gene in renal cell carcinoma by demethylation of Klotho via DNMT3a." (PMID 35127476, 2021). "Our study suggests that Sohlh2 and DNMT3a/Klotho can be used as potential targets for the clinical treatment of renal cell carcinoma." (PMID 35127476, 2021). "In renal cell carcinoma, Sohlh2 was positively correlated with Klotho and negatively correlated with DNMT3a." (PMID 35127476, 2021). "In order to determine the functions of DNA methyltransferase in kidney tumorigenesis on the molecular level, we examined the mRNA expression levels of DNMT1, DNMT3A, DNMT3B, and DNMT3B variants in renal cell carcinoma tissue." (PMID 28160561, 2017). "Finally, we collected 40 resected renal cell carcinoma samples to study the relevance between Sohlh2, DNMT3a, and Klotho by immunohistochemistry." (PMID 35127476, 2021). "Sohlh2 correlated with Klotho positively and with DNMT3a negatively in renal cell carcinoma." (PMID 35127476, 2021). "LncRNA SLERCC (Specific Low Expression in RCC) is lowly expressed in renal cell carcinoma via DNMT3A-mediated SLERCC promoter hypermethylation and its overexpression inhibits Wnt/β-catenin signaling and RCC metastasis." (PMID 38933287, 2023).
renal fibrosis (5 papers, 2021 to 2024). A final common manifestation of a wide variety of chronic kidney diseases characterized by glomerulosclerosis and tubulointerstitial fibrosis. "In the mouse models described by Jaiswal and Sano, the presence of variations in TET2 and DNMT3a was associated with greater glomerulosclerosis and greater renal fibrosis after exposure to angiotensin II." (PMID 37763205, 2023). "Hematopoietic TET2 or DNMT3A disruption promotes both cardiac and renal fibrosis in hypertensive cardiac remodeling mice model via elevated expression of inflammatory cytokines such as IL-6 and C-C motif chemokine 5 (CCL5)." (PMID 37928907, 2023). "Additionally, knockdown of DNMT3a restores TGF-β1’s inhibitory effect on PTEN activity in the TGF-β-induced renal fibrosis model mainly through controlling Klotho promoter methylation mediated by DNMT3a." (PMID 39165377, 2024). "Taken together, these results confirmed that DNMT3a-mediated TFEB promoter was hypermethylated, and demethylated by 5-Aza could recover fibrotic TFEB loss and alleviate renal fibrosis pathogenesis." (PMID 38481802, 2024). "Previous studies also demonstrated that pharmacologically reducing the interaction between DNMT3a and PTEN can significantly delay renal fibrosis." (PMID 39165377, 2024). "In the context of renal fibrosis, hydralazine was observed to downregulate mRNA expression of DNMT1 and induce expression of DNMT3a and Tet3." (PMID 33735324, 2021). "DNMT3A negatively regulates PTEN to activate the PI3K/AKT signaling pathway, induces epithelial-mesenchymal transition (EMT) in renal tubular epithelial cells, and aggravates renal fibrosis." (PMID 37928907, 2023).
Sepsis (5 papers, 2017 to 2023). Sepsis is defined as life-threatening organ dysfunction caused by a dysregulated host response to infection. "We thus examined the expression levels of DNMT1 and DNMT3A and found that both genes were significantly upregulated within the IECs of CS-injected sepsis mice compared to those of sham mice." (PMID 36899862, 2023). "EVs from septic shock patients carried more total DNMT mRNAs and more DNMT3A+DNMT3B mRNAs than control subjects or sepsis EVs." (PMID 38343439, 2023). "Upregulated DNMT1, DNMT3a and DNMT3b, resulting in global DNA hypermethylation methylation in sepsis." (PMID 34163486, 2021). "Melioidosis patients with a regular alcohol consumption habit also expressed significant down regulation of DNMT3A, apart from a similar differential expression of other markers compared to other sepsis cases." (PMID 28628607, 2017). "Our comparison of melioidosis patients with regular alcohol consumption habit (n = 8) and sepsis controls (n = 10) showed a similar expression pattern to the entire melioidosis cohort (n = 30), in addition to down regulated expression of DNMT3A and IL8." (PMID 28628607, 2017). "This can be achieved by the enzymatic activity of DNMT1 and DNMT3A in DNA methylations and/or by the posttranscriptional regulation of the miRNAs (such as miR-149-5p, miR-466q, miR-495, and miR-511-3p) upregulated in the sepsis IECs." (PMID 36899862, 2023). "It was observed that the EVs from patients in septic shock contained a higher quantity of total DNMT mRNAs, as well as DNMT3A+DNMT3B mRNAs, when compared to EVs from control subjects or individuals with sepsis." (PMID 38343439, 2023). "Humans with sepsis upregulate DNMT1, DNMT3a and DNMT3b, resulting in global DNA methylation differences, 82.6% of which are suppressive hypermethylated marks." (PMID 34163486, 2021). "Knock out DNMT3a, or Decabitine Restore CD8 + T cell effector function.Decabitine restore immune function and decreases mortality in sepsis." (PMID 34163486, 2021).
Weaver syndrome (5 papers, 2019 to 2024). Weaver syndrome (WVS) is a rare, multisystem disorder characterized by tall stature, a typical facial appearance (hypertelorism, retrognathia) and variable intellectual disability. "Similarly, an individual with a maternally inherited duplication encompassing DNMT3A exhibits a growth failure phenotype marked by developmental delay, despite also possessing a paternally inherited Weaver syndrome-related point mutation in EZH2." (PMID 31575610, 2019).
autoimmune disease (4 papers, 2018 to 2025). A disorder resulting from loss of function or tissue destruction of an organ or multiple organs, arising from humoral or cellular immune responses of the individual to their own tissue constituents. "Recently, CHIP—with the most common mutations in DNMT3A (29.5%)—was associated with an increased risk for autoimmune diseases (OR 6.6, 95% CI 1.7–30) in patients undergoing hip arthroplasty." (PMID 36618380, 2022). "DNMT3A, a DNA methyltransferase, is a very intriguing candidate gene for SLE as altered patterns of DNA methylation are reported in autoimmune diseases, and hypomethylation of apoptotic DNA has been reported to induce autoantibody production in SLE." (PMID 29177435, 2018).
Crohn disease (4 papers, 2013 to 2022). A gastrointestinal disorder characterized by chronic inflammation involving all layers of the intestinal wall, noncaseating granulomas affecting the intestinal wall and regional lymph nodes, and transmural fibrosis. "Moreover, the DNMT3A intronic polymorphism rs13428812, situated in the same LD block with our studied rs7590760, has been shown to contribute to Crohn’s disease." (PMID 23666104, 2013). "The results indicate not only the complex involvement of environmental but also genetic factors, which may act in synergy to reduce DNMT3A expression in Crohn ́s disease." (PMID 36271073, 2022). "We found that DNMT3A mRNA levels, but not DNMT3B nor DNMT1, were significantly reduced in both inflamed and non inflamed samples from Crohn ́s disease (CD), but also from ulcerative colitis patients, compared to healthy individuals." (PMID 36271073, 2022).
embryonal carcinoma (4 papers, 2014 to 2020). A non-seminomatous malignant germ cell tumor characterized by the presence of large germ cells with abundant cytoplasm resembling epithelial cells, geographic necrosis, high mitotic activity, and pseudoglandular and pseudopapillary structures formation. "They found that Dnmt3a2 is a shorter isoform of Dnmt3a and is the predominant type in embryonic stem cells and embryonal carcinoma cells, and it can also be found in testis, ovary, thymus, and spleen." (PMID 30333755, 2018). "In support of our conclusions, combined acute inactivation of DNMT3A/B does not lead to genome hypomethylation in human embryonic carcinoma cells." (PMID 32561758, 2020). "In turn, DNMT3A, along with DNMT3B, functions as a de novo methyltransferase that plays important roles in normal development especially during early embryogenesis, as well as in embryonic carcinoma cells." (PMID 31527824, 2019).
fibrosis (4 papers, 2020 to 2024). the formation of excess fibrous connective tissue in an organ or tissue in a reparative or reactive process. "In this analysis, hepatic expression of DNMT1, DNMT3a, and DNMT3b was significantly increased in individuals with fibrosis as compared to a control group of healthy individuals." (PMID 38722973, 2024). "The protein levels of FASN were also elevated in the patients with steatosis and further elevated in the patients with NASH-fibrosis, whereas protein levels of both DNMT3A and SHP were not significantly changed in these patients compared to normal subjects." (PMID 33235221, 2020).
head and neck squamous cell carcinoma (4 papers, 2017 to 2025). A squamous cell carcinoma that arises from any of the following anatomic sites: lip and oral cavity, nasal cavity, paranasal sinuses, pharynx, larynx, and salivary glands. "In head and neck squamous cell carcinoma (HNSC), the presence of HNRNPC, DNMT1, DNMT3A, ZC3H13, NSUN5, and IGF2BP2 highlights potential cross-talk between DNA and RNA methylation in immune modulation." (PMID 40565233, 2025).
hyperglycaemia (4 papers, 2016 to 2024). "We observed that three months of hyperglycaemia, in insulin-deficient Ins2Akita mice, decrease DNMT1 and DNMT3a expression levels." (PMID 30057682, 2018). "By contrast, three months of hyperglycaemia in insulin-deficient Ins2Akita mice resulted in the downregulation of DNMT1 and DNMT3a expression." (PMID 30057682, 2018). "While we did not reveal the dysregulation of DNMT expression using microarray data of short-term type 1 diabetes mouse models, three months of hyperglycaemia in insulin-deficient Ins2Akita mice resulted in the downregulation of DNMT1 and DNMT3a expression." (PMID 30057682, 2018).
inflammatory bowel disease (4 papers, 2022 to 2025). A spectrum of small and large bowel inflammatory diseases of unknown etiology. "Genetic variants in the DNA methyltransferase 3 A (DNMT3A) locus have been associated with inflammatory bowel disease (IBD)." (PMID 36271073, 2022). "Ulcerative colitis (UC), an inflammatory bowel disease, is also linked to CHIP, particularly with DNMT3A and PPM1D mutations, and is associated with an increased risk of ischemic heart disease." (PMID 39997650, 2025). "DNA methyltransferase 3 A (DNMT3A) is involved in DNA methylation, and genetic variants in the DNMT3 locus have been associated with inflammatory bowel disease." (PMID 36271073, 2022).
male infertility (4 papers, 2017 to 2025). The inability of the male to effect fertilization of an ovum after a specified period of unprotected intercourse. "Although DNMT3L does not have a catalytic subunit, it is an important co-activator of DNMT3a and B activity and Dnmt3l knockout has been shown to impair spermatogenesis and cause male infertility, a phenotype observed in F1." (PMID 34968297, 2021). "DNA methylation is carried out by the methyltransferase enzyme Dnmt3A in early germ cells, the loss of which results in male infertility due to meiotic failure." (PMID 32131873, 2020). "The purpose of this study was to investigate the association between male infertility and single-nucleotide polymorphisms (SNPs) of DNA methyltransferases (DNMT) genes (DNMT3B: rs2424909, DNMT1: rs4804490, DNMT3A: rs1550117 and DNMT3L: rs7354779)." (PMID 28894282, 2017).
monocytic leukemia (4 papers, 2013 to 2024). "In established HMA-resistant cell lines from a human monocytic leukemia cell line (MOLM-13), protein levels of DNMT3B were found upregulated compared to parental cell line and mRNA expression of DNMT1 and DNMT3A in HMA-resistant cell lines decreased compared to parental cell line." (PMID 31331399, 2019).
oral cancer (4 papers, 2014 to 2020). "In addition to being highly expressed in some oral cancer cell lines, DNMT3A was highly expressed in the normal cell line SG." (PMID 31624299, 2019). "From our microarray data, we also found that DNMT1, DNMT3A and DNMT3B were overexpression in oral cancer." (PMID 32238162, 2020).